GPR20 (G protein-coupled receptor 20)
Description:
Orphan receptor with constitutive G(i) signaling activity that activate cyclic AMP.
Tractability: Small molecule: it belongs to a druggable protein family. Antibody: UniProt places it where antibodies can reach, with high confidence; its Gene Ontology location is reachable by antibodies, with high confidence; UniProt predicts a signal peptide or a membrane-spanning region; the Human Protein Atlas places it where antibodies can reach.
Target class: Family A G protein-coupled receptor; Membrane receptor
Gene: Protein-coding gene on chromosome 8 (141,356,470 to 141,367,286, reverse strand). Ensembl gene ENSG00000204882.
Subcellular location: Cell membrane
Subcellular location (Human Protein Atlas): Plasma membrane
Pathways (Reactome):
Signal Transduction: G alpha (s) signalling events
Gene Ontology:
Molecular function: G protein-coupled receptor activity; protein binding
Biological process: G protein-coupled receptor signaling pathway
Cellular component: plasma membrane; receptor complex; membrane
Genetic constraint (gnomAD): Missense variants: 485 observed, 510.87 expected, observed/expected ratio (o/e) 0.95, 90% interval 0.88 to 1.02. Synonymous variants: 237 observed, 232.01 expected, observed/expected ratio (o/e) 1.02, 90% interval 0.92 to 1.14.
Homologues: Orthologues: chimpanzee GPR20 (99% identical), macaque GPR20 (97% identical), dog GPR20 (83% identical), guinea pig GPR20 (83% identical), mouse Gpr20 (83% identical), pig GPR20 (81% identical), rat Gpr20 (81% identical), zebrafish gpr20 (51% identical), tropical clawed frog gpr20 (49% identical). Paralogues in human: F2RL1 (25% identical), GPR17 (25% identical), F2RL3 (22% identical), LPAR6 (22% identical), GPR35 (22% identical), P2RY8 (22% identical), GPR18 (22% identical), P2RY10 (22% identical), F2R (21% identical), CYSLTR1 (21% identical), CYSLTR2 (20% identical), LPAR4 (20% identical), and 4 more.
Diseases named in the same sentence as GPR20 in open-access papers:
GPR20 is named in the same sentence as 8 diseases in open-access papers, as found by Europe PMC text mining. Sharing a sentence is not in itself a finding about the gene and the disease. The quoted sentences say what the papers report.
gastrointestinal stromal tumor (3 papers, 2023 to 2025). "DS-6157a is a G protein-coupled receptor 20 (GPR20)-directed ADC, and it was previously under investigation for the treatment of gastrointestinal stromal tumors (GISTs)." (PMID 40650299, 2025). "GPR20 is a class-A orphan G protein-coupled receptor (GPCR) and a potential therapeutic target for gastrointestinal stromal tumors (GIST) owing to its differentially high expression." (PMID 36849514, 2023). "Previous studies identified GPR20 as a novel non-tyrosine kinase target in gastrointestinal stromal tumors (GIST) given its differentially high expression." (PMID 36849514, 2023).
tumor (2 papers, 2024 to 2025). "The anti-GPR20 antibody-drug conjugate DS-6157a showed GPR20 expression-dependent anti-tumour activity in a variety of resistant lines (e.g., imatinib, sunitinib and regorafenib)." (PMID 39070147, 2024).
cancer (1 paper, 2023). A tumor composed of atypical neoplastic, often pleomorphic cells that invade other tissues. "Sacituzumab govitecan led to the validation of TROP2 as a target in TNBC, and SN-38-based ADCs in clinical evaluation highlight the potential of new targets in cancer types that were poorly represented in the ADC landscape (HER3, CEACAM5, B7-H3 and GPR20)." (PMID 36650546, 2023).
intestinal disorder (1 paper, 2023). A non-neoplastic or neoplastic disorder that affects the small or large intestine. "Moreover, as GPR20 shows therapeutic potential in GIST and other intestinal disorders, our structures may offer opportunity for rational drug discovery targeting GPR20 for related diseases." (PMID 36849514, 2023).
GPR20 also shares sentences with these, for which no sentence is quoted: cavernous hemangioma (1 paper); cervicitis (1); preeclampsia (1); squamous intraepithelial lesions (1).